HMGB1 (high mobility group box 1)
Diseases named in the same sentence as HMGB1 in open-access papers (continued):
Sharing a sentence is not in itself a finding about the gene and the disease.
peripheral neuropathy (12 papers, 2012 to 2025). A disorder affecting the peripheral nervous system. "We have reported that HMGB1 is involved in the peripheral neuropathy caused by paclitaxel or vincristine in mice and/or rats." (PMID 31666085, 2019). "Thus, the HMGB1-dependent peripheral neuropathy caused by oxaliplatin appears largely independent of macrophages, which is quite different from the critical role of macrophages in a mouse model for paclitaxel-induced peripheral neuropathy." (PMID 31666085, 2019). "DAPT relieved nab-PTX-induced peripheral neuropathy by inhibiting the activation of the HMGB1/caveolin-1 signaling pathways and decreasing the levels of inflammatory cytokines and oxidative stress in vivo and in vitro." (PMID 40291503, 2025). "All the results showed that the protective effect of DAPT on nab-PTX-induced peripheral neuropathy was related to inhibition of the Notch/HMGB1/caveolin-1 pathway." (PMID 40291503, 2025). "Macrophage-derived high mobility group box 1 (HMGB1), a damage-associated molecular pattern (DAMP) protein, plays a key role in the development of chemotherapy-induced peripheral neuropathy (CIPN) caused by paclitaxel in rodents." (PMID 31666085, 2019). "We previously demonstrated that HMGB1 plays a critical role in the development and maintenance of peripheral neuropathy following repeated administration of paclitaxel or vincristine in rats and/or mice." (PMID 31666085, 2019). "In the present study, we examined the roles of HMGB1 and macrophages in oxaliplatin-induced peripheral neuropathy in mice and analyzed the effect of TMα alone or in combination with various anticoagulants." (PMID 31666085, 2019). "Increased HMGB1 expression in the dorsal root ganglion (DRG) is critical for the development of peripheral neuropathy in type 1 diabetes." (PMID 31165005, 2019). "The present study demonstrates the critical role of HMGB1 in the development and maintenance of oxaliplatin-induced peripheral neuropathy, which is mediated by RAGE, TLR4, and CXCR4." (PMID 31666085, 2019). "More importantly, the use of the anti-inflammatory compound and known inhibitor of HMGB1, glycyrrhizin, has the ability to diminish persistent pain behavior in a model of peripheral neuropathy, presumably through its ability to neutralize the cyotkine." (PMID 22824385, 2012). "CIPN, an adverse impact that limits the dosage of commonly used chemotherapy drugs including paclitaxel, oxaliplatin, vincristine, and bortezomib, worths attention, in which HMGB1 is of great significance in the emergence and progression (HMGB1 and Chemotherapy-Induced Peripheral Neuropathy)." (PMID 39008169, 2024). "HMGB1 has been quantified in rodent models of painful peripheral neuropathies including PTTN." (PMID 33918407, 2021). "Our data thus suggests a causative role of HMGB1 derived from non-macrophage cells in oxaliplatin-induced peripheral neuropathy and a thrombin-dependent anti-neuropathic activity of exogenous TMα and, most probably, endogenous TM." (PMID 31666085, 2019). "Since thrombin is required for TMα-induced inhibition of the allodynia following intraplantar injection of HMGB1 in mice, we next tested whether the preventive effect of TMα against the oxaliplatin-induced peripheral neuropathy involves endogenous thrombin." (PMID 31666085, 2019). "Our previous study also found that inhibition of the Notch pathway could reduce the expression of inflammatory factors accompanied by repressive glia response through the HMGB1/TLR4 signalling pathway in a rat model of nab-paclitaxel-induced peripheral neuropathy." (PMID 36819745, 2023). "Most recently, we have demonstrated that inactivation of macrophage-derived HMGB1 by an anti-HMGB1-neutralizing antibody or a recombinant soluble form of human thrombomodulin (TM), referred to as TMα, completely prevents the development of paclitaxel-induced peripheral neuropathy." (PMID 31666085, 2019).
peripheral neuropathy (continued). "We next asked whether well-known, pro-nociceptive receptors for HMGB1, such as TLR4, RAGE, and CXCR4, contributed to the oxaliplatin-induced peripheral neuropathy." (PMID 31666085, 2019).
respiratory diseases (10 papers, 2017 to 2023). "High-mobility group box 1 (HMGB1) is a protein associated with inflammatory responses in various respiratory diseases and increased HMGB1 aggravates lung injury." (PMID 36186445, 2022). "In the following sections, we evaluate the role played by HMGB1, IL-33, and non-coding genetic material in the onset of the most important respiratory diseases." (PMID 36675299, 2023). "This underlines the importance of HMGB1 and the RAGE for respiratory diseases caused by type 2 immunoreactions." (PMID 36675299, 2023). "The persistent presence of PA and huge recruitment of neutrophils in the lung are associated with the elevated level of high mobility group box 1 (HMGB1) in airways in respiratory diseases." (PMID 28589151, 2017). "The purpose of our review is to highlight the alterations in respiratory diseases involving some alarmins, such as high mobility group box 1 (HMGB1) and interleukin (IL)-33, and their inter-relationships and relationships with genetic non-coding material, such as microRNAs." (PMID 36675299, 2023). "In conclusion, these findings suggest a novel mechanism of vagal sensory nerve dysfunction and plasticity secondary to tissue alarmin release, highlighting possible therapeutic avenues to explore targeting the HMGB1-RAGE signaling axis in patients with respiratory disease." (PMID 34621188, 2021). "Recent studies have shown that high mobility group box 1 (HMGB1) is involved in the occurrence and development of respiratory diseases, including COPD." (PMID 36301039, 2022). "In aspirin-exacerbated respiratory disease, CysLT2R signaling on platelets could use RAGE/HMGB1 as a link to the downstream type 2 respiratory immunopathology and IL-33-dependent mast cell activation typical of aspirin-exacerbated respiratory disease." (PMID 35008546, 2021).
adenocarcinoma (9 papers, 2012 to 2024). A common cancer characterized by the presence of malignant glandular cells. "Changes in SERPINE1, CDK1, ZWINT, and FN1 expression were validated using qRT-PCR after HMGB1 silencing or overexpression in PC-3 and LNCaP (selected as an adenocarcinoma model of PCa responding to hormonal treatment) cell lines." (PMID 38542079, 2024). "The recombinant Lj-HMGB1 (rLj-HMGB1) protein bound double-stranded DNA and induced the proliferation of human adenocarcinoma cells to a similar extent as human HMGB1." (PMID 22563397, 2012). "The data show that mutations and CNA affecting HMGB1, HMGB2, and the proteins identified in the corresponding Y2H interactome are more frequently present in neuroendocrine PCa and castration-resistant PCa than in adenocarcinoma." (PMID 31694235, 2019). "As the HEp-2 cells are derived from a human adenocarcinoma, and as the location of HMGB1 may predominate in the cytoplasm of malignant cells, this could be a plausible explanation for the cytoplasmic staining of HMGB1 in HEp-2 cells." (PMID 26596890, 2015). "The clinical relevance of HMGB1 and HMGB2 in the regulation of identified genes was explored in public databases comparing gene expression in PCa patient samples classified as adenocarcinoma or neuroendocrine types." (PMID 38542079, 2024). "We selected several oncogenes and one tumor suppressor gene, showing deregulation by HMGB proteins, for independent validation after HMGB1 or HMGB2 shRNA silencing or overexpression in PC-3, considered the model of SCNC PCa, and in the LNCaP cell line, considered the adenocarcinoma model." (PMID 38542079, 2024).
retinopathy (8 papers, 2014 to 2024). "Under diabetic conditions, HMGB1 is known to act as a pro-inflammatory cytokine that is involved in many diabetic complications such as retinopathy and nephropathy." (PMID 26950148, 2016). "We also tested HMGB-1 levels in the vitreous humor of control animals and animals with oxygen-induced retinal neovascularization, model of oxygen-induced retinopathy." (PMID 24498140, 2014). "Finally, to evaluate the role of HMGB-1 in retinal angiogenesis, we turned to a mouse model of oxygen-induced retinopathy." (PMID 24498140, 2014). "Therefore, the aim of our study was to investigate the effect of Cs-A on the retinopathy in a type 2 DM animal model and to elucidate its potential mechanism, specifically, to study the alternation of expression levels of HMGB-1, IL-1β and TNF-α in the retinal tissues." (PMID 32019593, 2020). "Our data also indicate that HMGB-1 is not involved in retinal neovascularization in the oxygen-induced retinopathy model." (PMID 24498140, 2014).
liver (7 papers, 2009 to 2022). "We also compared the sensitivity and specificity of serum HMGB1 with that of CEA, a well-known gastrointestinal tumor biomarker." (PMID 19476625, 2009).
vasculopathy (7 papers, 2019 to 2024). "These smooth muscle-specific Asah1 gene knockout mice were used to study the high mobility group box 1 (HMGB1) signaling axis in ACDase-deficiency-mediated vasculopathy." (PMID 36830643, 2023). "It has been found that blood levels of HMGB1 are elevated in patients with SSc and that HMGB1 maintains autophagy-associated activation of neutrophils, suggesting that neutrophil autophagy is involved in vasculopathy in SSc." (PMID 39559368, 2024). "Blockade of HMGB1 might represent a promising therapeutic target for the simultaneous inhibition of allograft chronic inflammatory damage and vasculopathy/fibrosis progression." (PMID 33777037, 2021).
psychiatric disorder (6 papers, 2020 to 2025). A disorder characterized by behavioral and/or psychological abnormalities, often accompanied by physical symptoms. "The role of HMGB1 has been studied in the context of some mental illnesses and has proven to be important for many of them." (PMID 37298365, 2023). "Despite theexclusion of comorbid psychiatric disorders in our study, the effect ofpsychosocial stress levels, which were found to affect serum HMGB1 levels, couldnot be evaluated." (PMID 41209506, 2025). "As can be seen from the examples above, HMGB1 may be an important biomarker of psychiatric diseases." (PMID 37298365, 2023). "Extracellular HMGB1 could then contribute to the development or maintenance, or both, of neuroinflammation that mediates psychiatric disorders such as MDD." (PMID 32344830, 2020). "Astrocyte-derived HMGB1 could then be involved in neuroinflammatory processes which, in turn, mediate psychiatric disorders such as MDD." (PMID 32344830, 2020). "Thus, HMGB1, and its upstream and downstream signaling molecules, may serve as therapeutic targets for the prevention or treatment of a number of psychiatric disorders." (PMID 32344830, 2020).
brain diseases (4 papers, 2014 to 2024). "In the present study, correlation between brain lesion volume and serum HMGB1 concentration was investigated in structural brain diseases in which inflammation occurs in the brain." (PMID 33150666, 2020). "Emerging studies find HMGB1 release contributes to induction of TLR and RAGE neuroimmune receptors as well as other neuroimmune genes, contributing to neurodegeneration in brain diseases, including AD and AUD." (PMID 33716687, 2021). "In contrast, serum HMGB1 levels of dogs with non‐epileptic brain diseases (median = 0.19 ng/mL; range, 0.03‐1.04) were not significantly increased compared to those of healthy dogs (P = .12)." (PMID 33150666, 2020). "Serum HMGB1 concentrations were significantly higher in epileptic dogs than in healthy dogs, but not in those nonepileptic dogs with brain disease." (PMID 33150666, 2020). "However, other components including etiology of structural brain disease, seizure frequency, brain lesion volume, seizure control status, and duration of treatment were not related to serum HMGB1 concentrations in epileptic dogs." (PMID 33150666, 2020).
central nervous system diseases (4 papers, 2018 to 2022). "It would be better to detect HMGB1 in cerebrospinal fluid where HMGB1 play the role in central nervous system diseases." (PMID 30139371, 2018).
inflammatory myopathies (4 papers, 2020 to 2026). "HMGB1 mediates activation of the innate immune response, including chemotaxis and proinflammatory cytokine release, and is involved in functional disturbances of muscle weakness in patients with inflammatory myopathy." (PMID 36497194, 2022). "In addition, the HMGB1-TLR4 pathways play an essential role in causing muscle fatigue in patients with myopathy because TLR4 is activated in mouse and human skeletal muscle fibers after HMGB1 stimulation." (PMID 36497194, 2022). "Inhibition of TLR4 and HMGB1 signaling significantly reduced the expression of TNF-α and IL-6 cytokines in a myopathy mouse model, suggesting that the HMGB1/TLR4 axis may involve in skeletal muscle atrophy." (PMID 36497194, 2022).
hematological malignancies (3 papers, 2020 to 2025). "In hematologic malignancies, HMGB1 promotes the formation of CSCs and chemoresistance through activation of inflammatory signaling pathways and modulation of the bone marrow microenvironment." (PMID 41354099, 2025). "Moreover, DNR, vincristine (VCR), etoposide (VP-16), cytosine arabinoside (Ara-C), adriamycin (ADM), and ATO can increase HMGB1 expression and promote chemoresistance in hematological malignancies." (PMID 32660524, 2020). "The dysfunction of HMGB1 may promote the occurrence and development of hematological malignancies by interfering with the hematopoietic function of the BM." (PMID 32660524, 2020). "HMGB1 could be released into the BM microenvironment by DCs as a potential immunomodulatory factor to bind with RAGE on the T cell surface and mediate the interaction between DCs and T cells, which is involved in the occurrence and development of hematological malignancies." (PMID 32660524, 2020).
hematological tumors (3 papers, 2021 to 2025). "Notably, HMGB1 induces neoangiogenesis in patients with solid tumours and other hematological neoplasms." (PMID 34445745, 2021). "In most hematological tumors, FOXP1 expression demonstrated a positive correlation with the expression levels of stimulatory immune genes such as ICOSLG, IL2RA, and HMGB1, and a negative correlation with the expression levels of inhibitory immune genes, such as SLAMF7." (PMID 40672953, 2025).
intestinal diseases (2 papers, 2021 to 2023). "In recent years, the association between HMGB1 and inflammation has been elucidated in various studies, including intestinal diseases." (PMID 34418984, 2021).
neurodevelopmental disorder (2 papers, 2021 to 2025). A behavioral and cognitive disorder with onset during the developmental period that involves impaired or aberrant development of intellectual, motor, or social functions. "It is not possible to predict the direct relationship between high HMGB1 levelsand neurodevelopmental disorders in ADHD in this study." (PMID 41209506, 2025). "Nevertheless, our findings support the hypothesis that HMGB1 could be a reliable inflammatory marker, explaining the link between inflammatory processes and several autistic traits, and therefore a possible therapeutic target in this neurodevelopmental disorder." (PMID 34198762, 2021).
musculoskeletal diseases (1 paper, 2017). "We hypothesised that HMGB1 staining would be increased in diseased tissues due to its pro-inflammatory and pathogenic role in some musculoskeletal disorders." (PMID 28761710, 2017).
HMGB1 also shares sentences with these, for which no sentence is quoted: acute myocardial infarction (14 papers); idiopathic pulmonary fibrosis (11); viral diseases (7); gestational diabetes mellitus (6); chronic periodontitis (5); dermatomyositis (5); Huntington disease (5); respiratory infection (4); thyroid (4); breast adenocarcinoma (3); cerebral malaria (3); cerebral oedema (3); colorectal adenocarcinoma (3); cutaneous melanoma (3); enterocolitis (3); gallbladder cancer (3); Glucose intolerance (3); Hypercholesterolemia (3); hypertrophy (3); mood disorder (3); neuromyelitis optica (3); Parkinson's (3); rectum adenocarcinoma (3); urothelial carcinoma (3); acute promyelocytic leukemia (2); amyloid (2); Anorexia (2); bacterial meningitis (2); blepharitis (2); bronchiolitis obliterans syndrome (2).
A further 197 diseases each share a sentence with HMGB1 in 2 papers or fewer.